PRDX6 (peroxiredoxin 6)
Diseases named in the same sentence as PRDX6 in open-access papers (continued):
Sharing a sentence is not in itself a finding about the gene and the disease.
tumor (continued). "Immunohistochemical analysis of ICC tumors and peritumoral tissues showed that PRDX6 expression was higher in tumor tissues than in peritumoral tissues." (PMID 36209344, 2022). "The mBc1 cluster expressed the pre-B cell receptor-associated molecule VPREB3, the B cell activation marker CD83, and genes associated with cell metabolism, cellular growth, and tumor progression (DDX54, PRDX6, GRHPR)." (PMID 36153593, 2022). "Immunostaining showed lower protein expression of Wnt7a, Wnt7b, Mmp7 and Ccnd2 in tumor tissues of the PRDX6 knockout group compared to the wild-type group." (PMID 36209344, 2022). "RNA sequencing data showed that 448 annotated genes were differentially expressed in tumor tissue of wild-type and PRDX6 knockout groups, including 127 upregulated genes and 321 downregulated genes (DEseq, fold change ≥ 1.5 and FDR ≤ 0.05)." (PMID 36209344, 2022). "Western blotting showed that the expression of PRDX6 in rat ICC tumor was higher than that in peritumoral tissue." (PMID 36209344, 2022). "The results demonstrated that PRDX1, PRDX4, PRDX5 and PRDX6 were significant difference between tumor and normal tissues, which were also validated in HPA database." (PMID 34246267, 2021). "As PRDX6 had high expression in tumor tissues with poor prognosis, and high genetic alterations rate in BLCA, then PRDX6 was selected to explore its roles in BLCA." (PMID 34246267, 2021). "Correlations between higher levels of PRDX1, PRDX4, PRDX6 and type 1, 2, and 6 infiltrates (C1, C2 and C6), suggesting the tumor promoting effect of these PRDXs." (PMID 34246267, 2021). "For example, the tumor volume of the PRDX6 overexpression group reached approximately 1600 mm3, which was significantly larger than that in the control group (only nearly 400 mm3)." (PMID 32201510, 2020). "Consistent with the results in vitro, PRDX6 overexpression significantly increased the tumor volume and weight compared to the control (P < 0.01)." (PMID 32201510, 2020). "Both peroxidase and PLA2 activities of Prdx6 were required for tumor development in xenografted mice lung in a process dependent on arachidonic acid (AA) release." (PMID 31652719, 2019). "It has also been reported that Prdx6 either enhance tumor multiplicity or reduce tumor number in mice skin cells, depending on the stage of tumor development." (PMID 31652719, 2019). "Its multiple functionality makes Prdx6 an important player in cell physiology and pathology and both peroxidase and PLA2 activities have been associated with tumor progression and dopaminergic neuron degeneration." (PMID 31652719, 2019). "Most reports point to a pro-proliferating and antiapoptotic action of Prdx6, but some studies have found the opposite effect, depending on the stage of tumor development." (PMID 31652719, 2019). "In our tumor tissues, we identified the sporadic expression of 9 detox proteins (encoded by seven genes), namely: SODC, CATA, PRDX2, PRDX6, GSTP1, ALDR and AK1BA." (PMID 28686225, 2017). "In an xenograft in vivo model, SVT (0.5 mg/kg and 1 mg/kg) also inhibited tumor growth accompanied with the reduction of PRDX6 expression, but increased expression of proapoptotic proteins." (PMID 26061816, 2015). "Thiacremonone also inhibited glutathione peroxidase activity of PRDX6 in normal and both PRDX6 overexpressed mice tumor tissues." (PMID 24618722, 2014). "On the other hand, we found an increase in tumor progression in Prdx6 overexpressing mice, most likely due to protection of tumor cells from inflammation-induced ROS damage and subsequent cell death." (PMID 25594034, 2014). "PRDX6 was decreased by treatment of thiacremonone in both normal and PRDX6 overexpressed mice tumor tissue." (PMID 24618722, 2014).
tumor (continued). "By hierarchical clustering, the expression of tumor associated antioxidants PPIA and Prdx6, and oxidative stress marker Nrf2 is more close to expression of Keap1." (PMID 24386210, 2013). "ROS detoxifying enzymes (e.g. catalase, peroxiredoxin 6, superoxide dismutase) were considerably upregulated in all tumor types." (PMID 22693581, 2012). "Two of the several proteins upregulated are alpha crystallin A (CRYAA) and peroxiredoxin 6 (PRDX6) which can inhibit apoptotic processes in tumor cells." (PMID 20844677, 2010). "In this study, we also demonstrated that PRDX6 enhanced orthotopic tumor growth and pulmonary metastasis in nude mice." (PMID 17980029, 2007). "The tumorigenicity and spontaneously metastatic capability regulated by peroxiredoxin 6 were determined using an orthotopic xenograft tumor model in athymic mice." (PMID 17980029, 2007). "To assess the phenotype of tumor cells in which PRDX6 expression was inhibited over a long-term period, we generated stable PRDX6-downregulated clonal cell lines." (PMID 17980029, 2007). "Investigations on tumor biopsies involving peroxiredoxin 6 are even rarer." (PMID 41187427, 2025). "A reduction in PRDX6 expression increases tumor cells’ sensitivity to ferroptosis inducers, indicating that PRDX6 may affect the sensitivity of cells to ferroptosis inducers." (PMID 40557156, 2025). "In the present study, both circ-231 and eIF4A3 were overexpressed in ESCC and participated in TPI1 and PRDX6 mRNA initial translation, suggesting that both circ-231 and eIF4A3 were involved in tumor progression via post-transcriptionally regulating the expression of TPI1 and PRDX6." (PMID 38577609, 2024). "Besides the physiological role of PRDX6, this enzyme has been described as contributing to carcinogenesis by enhancing tumor growth and increasing invasiveness and metastasis in different tumors." (PMID 39061949, 2024). "Indeed, PRDX6 downregulation is already considered a strategy to sensitize tumor cells to ferroptosis." (PMID 39061949, 2024). "In addition, we observed that among TCGA HCC cases, aberrant expression of PRDX6 predicts tumor progression and prognosis." (PMID 38544826, 2024). "In vitro, siRNA decreases the expression of PRDX6 and inhibits the growth of A549 cells, similar to mercaptosuccinate (a non-specific inhibitor of peroxidase activity), suggesting that PRDX6 promotes the growth of tumor cells through oxidase activity." (PMID 36611974, 2023). "As the negative regulator of ferroptosis, PRDX6 protects tumor cells by clearing PLOOH." (PMID 36611974, 2023). "Therefore, targeting PRDX6, thus disturbing redox balance in tumor cells, is a promising line of therapy." (PMID 36611974, 2023). "The team also demonstrated that PRDX6 promotes tumor cell proliferation through JAK2/STAT3." (PMID 36611974, 2023). "Moreover, the effects of PRDX2 regulation on intracellular signaling of PRDX6 have been correlated with different aspects of tumor behavior such as invasive, apoptosis, as well as, resistance to chemotherapeutic agents and tumor recurrence." (PMID 37501157, 2023). "Mean tumor area/total area was reduced in the PRDX6 knockout group compared to the wild-type group [46.169 ± 17.873 in wild-type rats (n = 8) vs. 10.651 ± 8.223 in PRDX6 knockout rats (n = 8)] (P < 0.001)." (PMID 36209344, 2022). "qRT-PCR was used to detect the knockout effect of PRDX6 in the model rat tumor tissues." (PMID 36209344, 2022). "Furthermore, the mRNA expression levels of PRDX1, PRDX4 and PRDX6 were closely related with tumor stage of BLCA." (PMID 34246267, 2021). "The 6-protein diagnostic panel consisted of FLNA, PRDX6 and ARHGDIB, associated with tumor growth, cell invasion and metastasis, GSTO1, having an antioxidant defense role (together with PRDX6), TUBA4A, found enriched in serum exosomes from NSCLC patients, and the tumor suppressor CDH13." (PMID 32575471, 2020).
tumor (continued). "Interestingly, loss of Prdx6 enhanced tumor multiplicity in the HPV8 model, while overexpression of Prdx6 significantly reduced the tumor number." (PMID 25594034, 2014). "The effect of PRDX6 expression on tumor growth and metastasis was further assayed in athymic mice." (PMID 17980029, 2007). "Notably, as a bifunctional protein, PRDX6 plays a critical role in tumor growth." (PMID 40164686, 2025). "It is noteworthy to mention that the presence of PRDX6 in blood may present as a tumor antigen." (PMID 40298631, 2025). "Therefore, PRDX6 could be the better choice as a target within the family of PRDXs since its removal may affect tumor cells with a minimal effect on normal ones." (PMID 39061949, 2024). "However, our observations with both tumor cell lines are consistent in that the lack of PRDX6 caused deficiencies in respiration and glycolysis, which seriously compromised the ability of these cells to divide, migrate, and invade." (PMID 37371884, 2023). "Therefore, the increase in AP-1 expression and activity may further up-regulate the expression of PRDX6 and promote tumor growth and invasion." (PMID 36611974, 2023). "Furthermore, PRDX6 genetic knockout significantly inhibited the tumor progression in rats." (PMID 36209344, 2022). "After identifying areas of interest in tumor and healthy tissues, we quantified NRF2 and peroxiredoxin 6 expression by measuring labeling intensity,revealing significant differences between tumor and healthy tissues." (PMID 41187427, 2025). "In conclusion, we found that the expression of PRDX6 in ICC was higher than in peritumoral tissues, which was related to the degree of tumor differentiation, tumor number and TNM stage." (PMID 36209344, 2022). "To explore the mechanism of action of PRDX6 in ICC, we performed RNA sequencing of tumor tissue from the livers of wild-type and PRDX6 knockout female rats 27 weeks after TAA modeling (n = 3)." (PMID 36209344, 2022). "All the gene signatures other than those of PRDX6 and HTATIP2 were correlated with tumour purity and B cell, CD4+ T cell, CD8+ T cell, macrophage, neutrophil and dendritic cell levels." (PMID 34760691, 2021). "Subsequently, the correlations between PRDXs and immune subtypes, tumor stemness demonstrated that PRDX1, PRDX4, PRDX6 were closely related with type C1, C2 and C6 infiltrates, while tumor stemness scores were positively with all PRDX members." (PMID 34246267, 2021). "SOD1, GLRX2, PRDX6, and GLRX3 genes were also overexpressed in MM patients compared to normal plasma cells, confirming that the redox status is unbalanced in tumour vs. normal cells." (PMID 33114738, 2020). "The increased effect of PRDX6 was further verified by growth markers, including PCNA, in tumor tissues." (PMID 32201510, 2020). "Results obtained with Prdx6 transgenic mice subjected to a model where tumors are induced with a mutagen (DMBA) and a tumor promoter (TPA) confirmed the tumor-preventive effect of this enzyme." (PMID 25594034, 2014). "PRDX6 showed dense methylation only in IVD; NDRG2 showed a significant methylation in cell lines and in tumour tissue compared to normal tissue, suggesting a potential epigenetic regulation of the gene." (PMID 19257893, 2009).
tumor (continued). "As a bifunctional protein, in addition to its role in redox balance, PRDX6 harbors both Ca2+-independent phospholipase A2 (iPLA2) and lysophosphatidylcholine acyltransferase (LPCAT) activities, which participate in tumor phospholipid remodeling to promote abnormal growth." (PMID 40164686, 2025). "However, inhibition of iPLA2β activity in tumor cells has been reported to induce GPX4-independent ferroptosis and iPLA2 activity of PRDX6 was a negative regulator of ferroptosis." (PMID 39601357, 2024). "To explain this arrest, we focused on the proliferating cell nuclear antigen (PCNA), whose expression level and redox state have been described to be altered by the lack of PRDX6 in other tumor cell lines." (PMID 39061949, 2024). "One of the main limitations of PRDX6 deletion is that although it reduces proliferation through cell cycle arrest, it does not seem to affect the viability of tumor cells." (PMID 39061949, 2024). "PRDX6, MAGOHB, NUCKS1, DCAF13, and TXN displayed opposite trends on their potential facilitation of CTL function as well as correlations with immune checkpoints and TILs (tumor-infiltrating lymphocytes) compared to ITGAL, ITGAX, and TMEM119 in NSCLC." (PMID 37835514, 2023). "Both PRDX6 peroxidase and PLA2 activity are involved in tumor development." (PMID 36209344, 2022). "From this cohort, 4 out of 5 of the proteins (IDH1, CTSD, PRDX6, and SERPINB6) also showed a statistically significant increase in abundance (12, 2.3, 2.6, and 3-fold, respectively) in the patient tumour samples when compared to the PDX F1 generation in the species-indistinguishable study." (PMID 30404163, 2018). "In both tumor models, Prdx6 activation had no influence on keratinocyte proliferation, apoptosis or the inflammatory response of the mice." (PMID 25594034, 2014). "This study aimed to assess whether the expression of NRF2 and Peroxiredoxin 6 could serve as predictive biomarkers of tumor response to treatment (surgery combined with radiotherapy), as evaluated by the absence of tumor progression at 24 months." (PMID 41187427, 2025). "Further functional assays confirmed that PRDX6 significantly promoted proliferation, migration, and invasion in both ER‐positive BRCA cells (MCF‐7) and TNBC cells (SUM159PT), and significantly accelerated tumor growth in vivo, supporting its oncogenic role irrespective of BRCA subtype." (PMID 40583735, 2025). "The challenge is to block Prdx6 expression in tumor cells without affecting normal cells." (PMID 39061949, 2024). "However, the activation of MAPK may elevate the aiPLA2 activity of PRDX6 and thus promote tumor cell growth." (PMID 36611974, 2023). "Therefore, genes VEGFA, ANXA1, HSP90B1, PSMA7, PRDX6, and PPP1CB may be new targets for anti-tumor effects in the future." (PMID 36741702, 2022). "The up-regulation of PRDX2, down-regulation of PRDX6, and the nuclear absence of PRDX1 in COAD tumor cells were indicated." (PMID 32231717, 2020). "Overall, The data show us that Keap1, Nrf2, PPIA, Prdx6 and CD147 were not correlated with tumor stage (T1 to T3), lymph node status (N0 to N1), pathological grade (GI to GIII) (P>0.05)." (PMID 24386210, 2013). "For instance, the human homologous genes for the murine genes upregulated by taxifolin in LL2 tumors, including Prdx6, Magohb, Nucks1, Dcaf13, and Txn1, acted to facilitate the CTL-mediated killing of tumor cells, as shown by their negative T cell dysfunction values." (PMID 37835514, 2023). "In addition, comparing with the cytoplasmic/ membranous and nuclear location of PRDX6 in normal cells, three of the COAD tissues showed an absence of nuclear PRDX6 in their tumor cells." (PMID 32231717, 2020).
infection (13 papers, 2012 to 2026). The state of being infected such as from the introduction of a foreign agent such as serum, vaccine, antigenic substance or organism. "PRDX6 also plays a role in immune defense, where it is upregulated in mice macrophages during infection, potentially to protect immune cells from oxidative damage." (PMID 38654712, 2024). "Using the Brucella suis S2 strain to infect RAW264.7 murine macrophages, the level of intracellular Prdx6 expression first decreased and later increased following infection." (PMID 31438945, 2019). "Especially, the levels of Trx and PRDX-6 were significantly higher at 72 h post infection, approximately 15-fold higher than in the control SUVECs, and the elevations showed a time-dependent manner after the CSFV infection." (PMID 25439655, 2014). "To address the question as to why a large change in Clara cell abundance did not result in a coincident large change in the overall levels of Prdx6, we monitored the levels of Prdx6 by immunostaining over the course of the infection." (PMID 22355371, 2012). "The avirulent S2 strain of B. suis, L. monocytogenes and the E. coli standard strain were used to infect RAW264.7 macrophage cells transfected with MmPrdx6 overexpression plasmids, and the total counts of viable bacteria and Prdx6 expression levels were detected at 2, 14 and 26 h post-infection." (PMID 31438945, 2019). "The results of these experiments also matched experiments in which an H26A mutant construct in a lentiviral vector was introduced into pulmonary microvascular cells from Prdx6 null mice, by infection, and compared with cells infected with wild-type construct or vector alone." (PMID 30934692, 2019). "By regulating the expression level of MmPrdx6 using overexpression and shRNA interference, intracellular bacterial levels in the RAW264.7 murine macrophage cell line infected with bacteria were detected to analyse the relationship between host Prdx6 and B. suis S2 strain infection." (PMID 31438945, 2019). "Thus, we evaluated the lungs from H26A-Prdx6 expressing mice and generated H26A-Prdx6 expressing pulmonary microvascular endothelial cells (PMVEC) by lentiviral infection of Prdx6 null cells to compare with wild type in the repair of lipid peroxidation." (PMID 28865296, 2018). "The Prdx6 enzymatic activities for infection with vector alone reflect values for Prdx6 null PMVEC." (PMID 28865296, 2018). "However, unexpectedly, prdx-6 mutant C. elegans are more resistant to other forms of oxidative stress, long-lived and resistant to infection with two opportunistic human pathogens; the gram-positive bacteria Staphylococcus aureus and the dimorphic yeast Candida albicans." (PMID 41702017, 2025). "Mouse pulmonary microvascular endothelial cells (MPMVECs) were obtained from the null mice and used in transfection or infection studies in which various expression constructs of wild-type or mutant Prdx6 could be introduced into the cells and their effects studied." (PMID 30934692, 2019). "Likewise, induction of Prdx6 in mouse AT1 cells may also provide a critical defense against infection-induced oxidative stress." (PMID 22355371, 2012). "In this assay, the antioxidant proteins thioredoxin (Trx), peroxiredoxin-6 (PRDX-6) and heme oxygenase-1 (HO-1) were examined at 24, 48 and 72 h post-infection." (PMID 25439655, 2014). "Specifically, both the Clara-enriched Prdx6 and the AT2-enriched Gpx3 are maintained, possibly by compensatory expression system during infection." (PMID 22355371, 2012). "Overall, CMA3p20 infection of BALB/c mice caused a significant decrease in the expression of the AOE genes in the lung tissue, specifically Cat, Gstm1, and Prdx6, while it did not affect Sod1 and Prdx1." (PMID 37022178, 2023). "In contrast to non-infected mice (lane 1–4), the level of PRDX6 steadily increased within 150 days post infection (lane 5–8)." (PMID 23210548, 2012).
infection (continued). "Prdx6 expression levels and the count of viable bacteria in macrophage cells increased 26 h later in the S2-infected group, but these phenomena did not occur after infection with L. monocytogenes and E. coli." (PMID 31438945, 2019).